CAD (carbamoyl-phosphate synthetase 2, aspartate transcarbamylase, and dihydroorotase)
Description:
Multifunctional protein that encodes the first 3 enzymatic activities of the de novo pyrimidine pathway: carbamoylphosphate synthetase (CPSase; EC 6.3.5.5), aspartate transcarbamylase (ATCase; EC 2.1.3.2) and dihydroorotase (DHOase; EC 3.5.2.3). The CPSase-function is accomplished in 2 steps, by a glutamine-dependent amidotransferase activity (GATase) that binds and cleaves glutamine to produce ammonia, followed by an ammonium-dependent carbamoyl phosphate synthetase, which reacts with the ammonia, hydrogencarbonate and ATP to form carbamoyl phosphate. The endogenously produced carbamoyl phosphate is sequestered and channeled to the ATCase active site. ATCase then catalyzes the formation of carbamoyl-L-aspartate from L-aspartate and carbamoyl phosphate. In the last step, DHOase catalyzes the cyclization of carbamoyl aspartate to dihydroorotate.
Synonyms: GATD4; CDG1Z; DEE50; EIEE50
Tractability: Small molecule: a structure with a bound ligand is known; it belongs to a druggable protein family. PROTAC: ubiquitination databases record sites on it; its protein half-life has been measured; a small molecule that binds it is known.
Target class: Enzyme
Gene: Protein-coding gene on chromosome 2 (27,217,369 to 27,243,943, forward strand). Ensembl gene ENSG00000084774.
Subcellular location: Cytoplasm; Nucleus
Subcellular location (Human Protein Atlas): Cytosol
Pathways (Reactome):
Metabolism: Pyrimidine biosynthesis
Gene Ontology:
Molecular function: aspartate carbamoyltransferase activity; carbamoyl-phosphate synthase (glutamine-hydrolyzing) activity; dihydroorotase activity; enzyme binding; identical protein binding; protein binding; zinc ion binding; aspartate binding; ATP binding; carbamoyl-phosphate synthase (ammonia) activity; glutaminase activity; protein kinase activity; amino acid binding; carboxyl- or carbamoyltransferase activity; hydrolase activity; hydrolase activity, acting on carbon-nitrogen (but not peptide) bonds; hydrolase activity, acting on carbon-nitrogen (but not peptide) bonds, in cyclic amides; metal ion binding
Biological process: 'de novo' pyrimidine nucleobase biosynthetic process; 'de novo' UMP biosynthetic process; UDP biosynthetic process; glutamine metabolic process; L-glutamine catabolic process; 'de novo' CTP biosynthetic process; amino acid metabolic process; animal organ regeneration; cellular response to epidermal growth factor stimulus; cellular response to xenobiotic stimulus; citrulline biosynthetic process; female pregnancy; heart development; lactation; liver development; nucleobase-containing small molecule metabolic process; organophosphate biosynthetic process; pyrimidine nucleoside biosynthetic process; pyrimidine-containing compound biosynthetic process; response to amine; response to caffeine; response to cortisol; response to insulin; response to starvation; response to testosterone; and 2 more
Cellular component: cytosol; extracellular exosome; membrane; nuclear matrix; nucleus; neuronal cell body; terminal bouton; cytoplasm; protein-containing complex
Genetic constraint (gnomAD): Loss-of-function variants: 78 observed, 230.36 expected, observed/expected ratio (o/e) 0.34, 90% interval 0.28 to 0.41. The upper end of that interval is the gene's LOEUF score, 0.41, which puts it in group 1 of 6, group 1 being the genes least tolerant of losing a copy. Missense variants: 2,159 observed, 3,030.6 expected, observed/expected ratio (o/e) 0.71, 90% interval 0.69 to 0.74. Synonymous variants: 1,189 observed, 1,203.4 expected, observed/expected ratio (o/e) 0.99, 90% interval 0.94 to 1.04.
Homologues: Orthologues: chimpanzee CAD (99% identical), macaque CAD (99% identical), pig CAD (97% identical), dog CAD (96% identical), mouse Cad (95% identical), rabbit CAD (95% identical), guinea pig CAD (95% identical), rat Cad (95% identical), tropical clawed frog cad (79% identical), zebrafish cad (77% identical), Drosophila melanogaster r (64% identical), Caenorhabditis elegans pyr-1 (57% identical). Paralogues in human: CPS1 (34% identical), OTC (5% identical).
Diseases named in the same sentence as CAD in open-access papers:
CAD is named in the same sentence as 104 diseases in open-access papers, as found by Europe PMC text mining. Sharing a sentence is not in itself a finding about the gene and the disease. The quoted sentences say what the papers report.
hepatocellular carcinoma (10 papers, 2015 to 2025). A malignant tumor that arises from hepatocytes. "In cancer biology, the overexpression of CAD, the multifunctional enzyme complex that includes DHOase, has been linked to poor prognosis in aggressive cancers such as glioblastoma and hepatocellular carcinoma." (PMID 39941127, 2025). "In oncology, the upregulation of CAD has been observed in glioblastoma and hepatocellular carcinoma." (PMID 39941127, 2025). "Previous preclinical studies in vitro show an increase in migration and invasion after l-CaD knockdown in lung cancer, gastric cancer, breast cancer, hepatocellular carcinoma, and PCa cells in contrast to our results." (PMID 37573448, 2023). "It is reported PFTK1 overexpression can increase CaD phosphorylation and enhance CaD to bind to F-actins, which promote hepatocellular carcinoma cells migration." (PMID 26488471, 2015). "CPS1 has been demonstrated to be downregulated in hepatocellular carcinoma by hypermethylation of the CPS1 promoter, whereas CAD mRNA levels were increased in HCC tissue." (PMID 33670206, 2021).
breast cancer (7 papers, 2015 to 2024). A primary or metastatic malignant neoplasm involving the breast. "For example, CAD expression is associated with poorer prognosis in patients with oral squamous cell carcinoma and colorectal cancer, whereas other studies with human colon and breast cancer cell lines, and gastric cancer show the function of CAD as a repressor of cancer cell migration or invasion." (PMID 26430961, 2015). "Palbociclib49, an FDA-approved CDK4/6 inhibitor for breast cancer, blocked S1900 phosphorylation of CAD in KSHV de novo infected HOKs and KSHV-positive BCBL-1 lymphoma cells." (PMID 38365882, 2024). "Currently, most of the available data on the role of CaD in carcinogenesis suggests that CaD, particularly l-CaD, plays an oncogenic role in many types of cancer such as breast cancer and colorectal cancer." (PMID 36768598, 2023). "In contrast, CAD was reported to suppress cancer cell invasion by regulating podosome/invadopodium formation in colon and breast cancer cell lines or by regulating phosphorylation through type I cGMP-dependent protein kinase in breast cancer cells." (PMID 26430961, 2015).
diabetes (6 papers, 2017 to 2025). "CaD also prevents glutamate accumulation by inhibiting diabetes-induced downregulation of the glutamate/l-aspartate transporter (GLAST)." (PMID 40465771, 2025). "In line with reduced levels of pro-inflammatory mediators, an increased amount of F4/80 positive macrophages in the interstitial areas of diabetic kidney was significantly reduced in CaD treated mice." (PMID 31935212, 2020). "Diabetes increases tyrosine nitration in the retina, fundamentally in the ganglion cell layer, and treatment with CaD attenuates this increase in tyrosine nitration initiated by diabetes." (PMID 30962865, 2019). "The regulation of diabetes is caused by genes including ASNS, CAD, GMPS, and PHGDH." (PMID 33490239, 2020). "Even though more evidence is needed to better understand the role of CaD in other diabetes-related microangiopathies such as DN, recent findings have demonstrated a strong rationale for its use in reducing UAER and markers of inflammation as well as improving endothelial function." (PMID 29082239, 2017). "Consequently, we hypothesized that CaD might reduce monocyte-to-macrophage differentiation, one specific hallmark of inflammation (and atherosclerosis) that involves signaling via PKCδ and MAPK, previously shown as mediators of CaD activity in a diabetes model." (PMID 34829669, 2021). "We showed that CaD significantly blocked VEGF and diabetes-induced VEGFR-2 phosphorylation, which is the main mediator of proliferation, migration, survival, and permeability in endothelial cells." (PMID 31935212, 2020). "Our proposed mechanism explains not only the CaD inhibitory effect on VEGF, but also the low rate of adverse effects as compared to VEGF antibodies in diabetes." (PMID 31935212, 2020).
Epileptic encephalopathy (6 papers, 2018 to 2025). A condition in which epileptiform abnormalities are believed to contribute to the progressive disturbance in cerebral function. "In fact, the current protocol should be regularly updated in order to accommodate newly discovery IEMs, such as uridine-responsive encephalopathy due to biallelic CAD mutations and vitamin B6-responsive epileptic encephalopathy due to biallelic PLPBP mutations." (PMID 30559706, 2018). "Furthermore, CAD-deficient Bengal cats might serve as a valuable spontaneous large animal model to further investigate the pathogenic mechanisms of this rare epileptic encephalopathy in humans." (PMID 40251393, 2025).
gastric cancer (6 papers, 2014 to 2025). A primary or metastatic malignant neoplasm involving the stomach. "Overexpressing CAD or mutating Asp1371 to block caspase-3 cleavage confers chemoresistance in xenograft and Cldn18-ATK gastric cancer models." (PMID 40442064, 2025). "The key enzymes involved in up-regulating pyrimidine synthesis, CAD and DHODH, are implicated in enhancing the chemoresistance of gastric cancer by accelerating glycolysis." (PMID 38728242, 2024). "Similarly, CAD expression in gastric cancer was lower in lymph node metastatic tissue compared to primary gastric cancer tissue, while overexpression of CAD in a lymph node metastatic gastric cancer cell line led to decrease in cell migration and invasion." (PMID 26430961, 2015).
melanoma (6 papers, 2012 to 2023). A malignant, usually aggressive tumor composed of atypical, neoplastic melanocytes. "We found that GREB1 Is4 is localized to the cytosol of cells and binds to CAD in melanoma cells, resulting in positive cooperation for pyrimidine biogenesis." (PMID 37658191, 2023). "In malignant melanoma patients, the expression of h-CaD was inversely correlated with the frequency of metastasis and positively correlated with the survival rate." (PMID 23241148, 2012). "Defective expression of h-CaD was therefore suggested as a marker for metastatic potential and poor prognosis in melanoma." (PMID 23241148, 2012). "The suppression of h-CaD expression in the blood vessels in malignant melanoma implies structural fragility of the vessels, which could result in their easy penetration by tumor cells." (PMID 23241148, 2012).
colon cancer (5 papers, 2012 to 2025). "In conclusion, our data clarified which CaD isoform is expressed in colon cancer and its subcellular localization." (PMID 36768598, 2023). "In this study, three key genes, ASNS, CEBPA, and CAD, were screened by Cox regression analysis in colon cancer." (PMID 35174151, 2022). "We further examined the expression of ASNS, CEBPA, and CAD in tumor tissues and adjacent normal tissues from different colon cancer patients." (PMID 35174151, 2022). "Western blot analysis revealed that two isoforms of CaD, h-CaD (80 kDa) and l-CaD (65 kDa) were dominantly expressed in colon cancer tissues." (PMID 23241148, 2012). "We herein report altered expression of CaD in tissues from the patients with colon cancer, and discuss its possible effects on tumor malignancy, such as poor response to chemoradiation therapy." (PMID 23241148, 2012). "Based on the expression profiles of ASNS, CEBPA, and CAD, 415 TCGA colon cancer samples were analyzed by consistent clustering and tSNE algorithm, and the samples were divided into two clusters, Cluster 1 and Cluster 2, with longer and shorter survival time, respectively." (PMID 35174151, 2022). "Expression level of CaD was also investigated in in thirteen human colon cancer cell lines." (PMID 23241148, 2012). "In a recent proteome assessment we found the clue that aberrant expression of CaD isoforms in colon cancer may link to tumor malignancy." (PMID 23241148, 2012). "Our present results cannot clearly assign the role(s) of individual CaD iosforms in colon cancer, but suggest that differential expression of isoforms may be one of the causes leading to tumor characteristics." (PMID 23241148, 2012). "Congruently, we observed an upregulation of CAD in CRC tissues, and a high level of CAD was found to correlate with poor survival in colon cancer based on the TCGA database." (PMID 40190348, 2025). "There are also contrasting data on the role of CaD in colorectal cancer, as it has been shown to exert tumor suppressor functions in the HCA7 colon cancer cell line." (PMID 36768598, 2023).
glioblastoma (5 papers, 2021 to 2025). The most malignant astrocytic tumor (WHO grade IV). "Also, targeting CAD can inhibit glioblastoma stem cells’ survival, self-renewal, and in vivo tumor initiation." (PMID 40190348, 2025). "Interestingly, it has recently been demonstrated that targeting pyrimidine synthesis at different levels, including inhibiting CAD, reduced the growth of glioblastoma cells in a rodent model." (PMID 33670206, 2021).
lung cancer (5 papers, 2020 to 2025). A malignant neoplasm involving the lung. "Recent studies have shown that natural products like kaempferol and plumbagin can inhibit Klebsiella pneumoniae DHOase, while the lung cancer drug afatinib has been found to inhibit CAD enzyme activity." (PMID 39941127, 2025). "The detailed mechanism for GR-induced upregulation in PCa is not known, but interestingly previous work shows that activated GR binds to CALD1 promoter in lung cancer cells, providing a mechanism for l-CaD upregulation by GR." (PMID 37573448, 2023). "In cancer therapy, the lung cancer drug afatinib has been reported to inhibit CAD activity, yet its precise mechanism of inhibition remains unclear and requires further structural characterization." (PMID 39941127, 2025). "Furthermore, we found that pyrimidine metabolic rate–limiting enzymes CAD, RRM2, DTYMK, TYMS, TK2, and NR5C2 were all associated with the clinical outcomes of lung cancer and liver cancer." (PMID 32638267, 2020). "Compared with the lung normal tissues, the pyrimidine metabolic rate–limiting enzymes CAD, RRM2, and TK1 were hypo-methylated in lung cancer tissues derived from GSE32867 dataset." (PMID 32638267, 2020). "Similar results were obtained in GSE62948 dataset that the DNA methylation intensity of CAD, RRM2, and TK1 was lower in lung cancer tissues, compared with normal lung tissues." (PMID 32638267, 2020).
atherosclerosis (4 papers, 2010 to 2021). A disease characterized by the build-up of fatty material and calcium deposition in the arterial wall resulting in partial or complete occlusion of the arterial lumen. "For SMCs, in particular, our findings suggest that mutations at CaD phosphorylation sites serve as a novel therapeutic strategy to combat vascular diseases such as atherosclerosis and restenosis." (PMID 20128924, 2010). "Given the importance of inflammation in atherosclerosis pathogenesis, our data suggest CaD as a promising inhibitor of atherosclerosis development and progression." (PMID 34829669, 2021). "Given the importance of inflammation, macrophage activation, and MMP9 activity in atherosclerosis pathogenesis, our data suggest a promising potential of CaD as an anti-atherosclerotic agent." (PMID 34829669, 2021). "Therefore, our results further suggest that CaD’s ability to suppress PKCδ activation may likewise provide advantages in modulating the process of atherosclerosis." (PMID 34829669, 2021). "Our study further suggests that CaD with combined mutations at both PAK- and Erk-sites (e.g., A1234) may serve as a more effective therapeutic reagent in cancer and proliferative vascular diseases such as atherosclerosis and restenosis." (PMID 20128924, 2010).
colorectal cancer (4 papers, 2012 to 2025). A primary or metastatic malignant neoplasm that affects the colon or rectum. "Although HCA7 is known to have unclassical characteristics compared to other colorectal cancer cell lines, and there was no clinical correlation in that study, these data cast some doubt regarding the role of CaD in colorectal cancer." (PMID 36768598, 2023). "Collectively, these data clarify how the expression patterns of CaD isoforms in colorectal cancer can have applications in the management of colorectal cancer patients." (PMID 36768598, 2023). "We confirmed that the expressed form of CaD in colorectal carcinoma cells is l-CaD, which was overexpressed in the majority of cases, while h-CaD was limited to smooth muscle cells." (PMID 36768598, 2023). "Relative expression levels of CaD in normal colorectal mucosa, colorectal cancers, normal liver, and the corresponding liver metastases (n = 10 per group) were determined by normalization to actin expression." (PMID 23241148, 2012). "Moreover, in colorectal cancer, CAD is regulated by MYC and when the metabolic reprogramming observed in cancer cells as a result of MYC activation is inhibited, cell growth is blocked by shutting down CAD and other enzymes of pyrimidine biosynthesis." (PMID 36295658, 2022). "Here, we analyzed a large cohort of colorectal cancer cases and found that cancer cells expressed l-CaD at various levels but not h-CaD, which is expressed only in the smooth muscle of visceral and vascular origins." (PMID 36768598, 2023). "The literature data suggest that CaD plays an important role in cancer development and progression, but the expression pattern and subcellular localization of both h-CaD and l-CaD in colorectal cancer have not been studied in tumor tissue thus far." (PMID 36768598, 2023). "Most studies have suggested an oncogenic role of CaD in colorectal cancer, but the exact subcellular localization of the two CaD isoforms in tumor cells and stroma have not been clarified yet." (PMID 36768598, 2023). "Furthermore, the expression patterns and subcellular localization of both h-CaD and l-CaD in colorectal cancer tissue have not yet been studied." (PMID 36768598, 2023).
diabetic retinopathy (4 papers, 2019 to 2021). "Although the beneficial effects of CaD in diabetic microangiopathy (e.g., diabetic retinopathy, nephropathy, and neuropathy) have been well-known, we study for first-time documents that CaD protects cardiomyocytes from HG+PA induced injury and Ca2+ mishandling." (PMID 33604360, 2021). "However, as demonstrated in diabetic retinopathy, the retina blood barrier breakdown allows the entry of CaD, which protects retina neurons." (PMID 33922431, 2021). "In diabetic retinopathy, studies have confirmed that CaD may protect the retina and reduce chemotaxis and aggregation of retinal inflammatory cells by inhibiting NF-κB and p38 MAPK activity." (PMID 31780874, 2019). "Similar results have been reported, in which CaD significantly inhibited FGF-induced ERK phosphorylation in glioma cells and P38 in diabetic retinopathy." (PMID 31935212, 2020).